BRCA1 (BRCA1 DNA repair associated)
Diseases named in the same sentence as BRCA1 in open-access papers (continued):
Sharing a sentence is not in itself a finding about the gene and the disease.
breast cancer (continued). "Indeed, forced expression of wild-type BRCA1 in breast cancer cell lines silenced FOXC1, whereas GATA3 knockdown induced its expression." (PMID 30764547, 2019). "Compared with the therapeutic response in overall enrolled patients, ORR was markedly higher in BRCA1/2 mutated patients (ORR of BRCA1/2 mutated vs. overall patients in breast cancer cohort, 67% vs. 29%; ORR of BRCA1/2 mutated vs. overall patients in ovarian cancer cohort, 45% vs. 25%)." (PMID 31521196, 2019). "In fact, 42% of breast cancer cases in BRCA1 mutation carriers are TNBC compared to 15–20% in non-BRCA-mutated breast cancers." (PMID 31775907, 2019). "Expression of immunostimulator and immunoinhibitor molecules, other than PD-L1 and PD-1, respectively, were generally increased in BRCA1-deficient breast cancers, but not in BRCA2-deficient breast cancers, compared to BRCA-proficient breast cancers." (PMID 31022191, 2019). "In otherwise histologically normal tissue of BRCA1 mutation carriers, luminal progenitors positive for RANK expression were shown to be highly proliferative, aberrant in DNA repair, and possessed a basal‐like breast cancer molecular signature." (PMID 31267556, 2019). "However, pathological high-grade breast cancers and TNBC often showed somatic mutations or abnormal expression of BRCA1 or BRCA2." (PMID 30828495, 2019). "However, economic evaluation results indicate that precautionary testing for BRCA1/2 is cost-effective with an ICUR of $9,000/QALY) even in healthy/unaffected women with a family risk of breast cancer." (PMID 31427963, 2019). "Considering the type of gene altered in relation to the cancer type or the cancer family history of the patient, we observed a high prevalence of BRCA1 and BRCA2 pathogenic variants in both patients with personal and family history of breast cancer (12.6% (97/768) and 8.7% (9/103), respectively)." (PMID 31159747, 2019). "Although studies in breast cancer show an interaction between BRCA1 and PR leading to an inhibition of PR activity on gene expression and cell proliferation, there is limited information on how BRCA1 influences PR signaling in benign breast tissue." (PMID 31771627, 2019). "To determine whether down-regulation of BRCA1 could affect breast cancer stem cell fate, we knocked-down BRCA1 in the BRCA1-competent human breast cancer cell line SKBR3 using RNA interference." (PMID 31273285, 2019). "Similarly, the median number of mutations in TCGA BRCA1- and BRCA2-deficient breast cancers being 2.2 and 2.0 fold higher, respectively, compared to BRCA-proficient breast cancers (P = 6.6 x 10−9 and 6.0 x 10−6, respectively)." (PMID 31022191, 2019).
breast cancer (continued). "Interestingly, reflective of our “Discovery-TNBC” cohort data, CCNE1 amplification in TNBC is mutually exclusive with BRCA1/2 mutations in both METABRIC and TCGA breast cancer databases." (PMID 30665374, 2019). "Similarly, BRCA1- and BRCA2-deficient breast cancers from TCGA had 0.31 and 0.33 median proportion of signature 3 compared to median of 0 in BRCA-proficient breast cancers (P = 3.5 x 10−20 and 3.4 x 10−18, respectively)." (PMID 31022191, 2019). "To date, only one literature reported that up-regulation of miR-125a-3p could advance docetaxel sensitivity of breast cancer cells through modulation of BRCA1 signaling." (PMID 30761271, 2019). "Poly(ADP-ribose) polymerase (PARP) plays a major role in single-strand DNA repair, and PARP inhibitors have demonstrated antitumor activity in HER2-negative metastatic breast cancer patients, associated with BRCA1/2 germline mutations." (PMID 31336685, 2019). "In addition, BRCA1 has also been found to repress ERα gene expression, which has been a point of focus for hormone-related cancers, such as breast cancer." (PMID 31771139, 2019). "Interestingly, differential apoptotic response to IFN-γ dependent on the presence of functional BRCA1 was previously observed in the HCC1937 isogenic breast cancer model, although the mechanism responsible for this phenomenon was not elucidated." (PMID 31840082, 2019). "We also note that the expression of BRCA1 and Xist are inversely correlated in breast cancer cell lines, raising the possibility that changes in BRCA1 activity might underlie the increased Xist expression in the TIA1+/− cells." (PMID 31875547, 2019). "This study aimed at identifying inherited pathogenic variants in breast cancer cases from Puerto Rico that were not linked to BRCA1 or BRCA2." (PMID 31780696, 2019). "Notably, 1 female (Patient ID: CRC629) with a BRCA1 mutation (c.5329dupC (also known as c.5382insC)/p.Gln1777ProfsTer74, 0.8%) with primary multiple cancer (CRC, ovarian, and breast cancer) had a family history of ovarian cancer." (PMID 31428572, 2019). "Increased basic knowledge of the mechanisms of glioma development could also help discover novel therapeutic targets, in analogy with how PARP inhibitors were discovered as a therapy in BRCA1 positive breast cancer patients." (PMID 31842352, 2019). "However, it should be taken into account that standard chemotherapy is likely to be applied as long as more information on the effect of platinum chemotherapy be available for subjects with positive hormone receptor breast cancer carrying BRCA1/2mutations." (PMID 30975222, 2019). "In accordance with decreased BRCA1 expression, TG or TT allele patients demonstrated elevated breast cancer risk relative to nonvariant patients (OR = 1.4; CI 1.1–1.8)." (PMID 30897768, 2019). "BRCA1 and BRCA2 gene mutations are associated with ovarian and breast cancer." (PMID 30362670, 2019). "Defects in BER related to low XRCC1 expression may sensitize breast cancer cells to PARPi, similar to homologous recombination and BRCA1/2 defects." (PMID 31596905, 2019). "Accordingly, we speculate that differential expression of Rb family members and/or posttranslational modifications of Rb that regulate interactions with E2F family members may contribute to the disparate regulation of BRCA1 in ovarian versus breast cancer." (PMID 31604914, 2019). "In this study, we examined the role of BRCA1 in the regulation of breast cancer cell stemness." (PMID 31273285, 2019). "No selection was made regarding a woman’s BRCA1/BRCA2 status or other genetic predispositions to breast cancer." (PMID 31491032, 2019). "As BRCA1 and ZBRK1 deficiency contributed to the progression of breast cancer, we supposed that this effect might be partially dependent on its functions in metabolism regulations." (PMID 30714292, 2019). "Future work may be warranted to investigate additional mechanism by which BRCA1- and BRCA2-deficient breast cancers give rise to different immunophenotype." (PMID 31022191, 2019).
breast cancer (continued). "In addition, Tax1 sensitizes breast cancer cells to malignant transformation induced by environmental carcinogens through the inhibition of estrogen-induced ERα-mediated BRCA1 expression." (PMID 31244317, 2019). "Taken together, these studies show frequencies of RECQL loss of function variants of 0–2.6% in patients with high-risk familial breast cancer who have previously tested negative for mutations in BRCA1/BRCA2 and other hereditary breast cancer genes." (PMID 30610487, 2019). "The mutations BRCA1 and BRCA2 are the most notable mutations implicated in breast cancer." (PMID 31183268, 2019). "Furthermore, the efficacy of a progesterone receptor antagonist mifepristone (RU486) has been shown to be effective in preventing mammary tumors in BRCA1 null mice." (PMID 31771627, 2019). "The triple negative tumour phenotype in breast cancer was statistically associated to 9–12 del BRCA1 carriers, when compared with the group of non-carriers (73% versus 21%, p = 0.0005; two-sided Fisher's exact test)." (PMID 31545835, 2019). "While most cancers with BRCA1 mutation are TNBC, cancers associated with BRCA2 may display all subtypes of breast cancer, with a similar frequency as in sporadic subtypes." (PMID 31336685, 2019). "This indicates that breast cancer and the BRCA1 mutation (and not cancer alone) are associated with the induction of antioxidant mechanisms." (PMID 31597313, 2019). "Our study also indicates the potential suitability of the salivary parameters of oxidative stress in the differential diagnosis of breast cancer patients with/without the BRCA1 mutation." (PMID 31597313, 2019). "We treated the genetically matched pair of parental (Vector) cells and the BRCA1-reconstituted HCC1937 breast cancer cells with SAHA44, a broad spectrum HDAC inhibitors and an FDA approved anti-cancer drug (Vorinostat), under normoxia and hypoxia, respectively." (PMID 31273285, 2019). "While the reason for this discrepancy remains unknown, similar findings have been previously reported in breast cancer cell lines where increased methylation at the BRCA1 promoter was observed after inoculation into immunodeficient mice." (PMID 31117198, 2019). "Thus, risk-stratified breast cancer screening can be enhanced by better classification of variants identified in BRCA1, BRCA2, and other breast cancer genes." (PMID 30832243, 2019). "Levels of AGE were slightly increased in women with breast cancer without the BRCA1 mutation, but the difference was insignificant." (PMID 31597313, 2019). "Hence, our goal for this study was to test the relationship between BRCA1 status and sensitivity to mTORC2 inhibition in breast cancer." (PMID 31771139, 2019). "Besides germline mutations in cancer-predisposing genes including BRCA1 and BRCA2, the most significant determinants of breast cancer risk are reproductive history and mammographic density." (PMID 30893315, 2019). "The association of CASP8 with breast cancer depended on BRCA1/BRCA2 mutation carrier status in some studies, but not others." (PMID 30601841, 2019). "It is unclear how PR functions in the background of BRCA1 mutations in non-cancerous benign mammary cells before breast cancer develops." (PMID 31771627, 2019).
breast cancer (continued). "Hereditary breast cancers constitute about 5–10% of all BC cases but pathogenic variants in the high-risk (RR ≥ 4) breast cancer susceptibility genes BRCA1 [OMIM 113705] and BRCA2 [OMIM 600185] account for approximately 50% (0.7–29% BRCA1 and 1.5–25% BRCA2) of all hereditary breast cancers." (PMID 31013702, 2019). "For example, there was no BRCA1/2 LGR variants detected in Ashkenazi Jewish familial breast cancer patients, but in non-Ashkenazi Jewish, the frequency of LGRs was 6%." (PMID 31174498, 2019). "Non-mutational deficiencies in BRCA1 can also exist due to down-regulation caused by promoter hypermethylation observed in 30–40% of sporadic breast cancer cases." (PMID 31890056, 2019). "The salivary buffer capacity was highest in healthy women without the BRCA1 mutation, and much lower in patients with the BRCA1 mutation and those without the mutation but suffering from breast cancer." (PMID 31597313, 2019). "This analysis allowed us to identify that BRCA1 was mainly correlated with triple negativity (OR: 17.31), presence of bilateral breast cancer history (OR: 4.96), occurrence of ovarian cancer (OR: 4.32) and presence of more than three breast cancer cases in the family (OR: 1.42)." (PMID 31244284, 2019). "It is noteworthy that an on-going clinical trial is investigating the association of inherited mutations in DNA repair genes, including BRCA1 and BRCA2, with PD-L1 expression and immune cells in breast cancer patients (ClinicalTrials.gov identifier: NCT03495544)." (PMID 31022191, 2019). "Indeed, BRCA1- and BRCA2-deficient breast cancers were found to be enriched for CIN25 signature that is a biomarker for chromosomal instability." (PMID 31022191, 2019). "We determined whether some of the commonly silenced breast cancer tumor suppressor genes were differentially expressed in the mammary tumors between control and HF offspring, specifically BRCA1, CDKN2A, and PTEN." (PMID 31889127, 2019). "In addition, the exposure of breast cell lines to ω-3 PUFA (EPA and DHA) was related to the increase in the expression of two breast cancer suppressor genes, namely BRCA1 and BRCA2." (PMID 31505792, 2019). "Collectively, these data suggest that the differences in immunophenotype between BRCA1- and BRCA2-deficient breast cancers may be attributed, in part, to PTEN gene mutation." (PMID 31022191, 2019). "Pathogenic variants in the two major breast cancer susceptibility genes BRCA1 and BRCA2 may explain 15% of increased risk of breast cancer among female relatives of breast cancer patients." (PMID 30689231, 2019). "Given the molecular similarities between HGSOC and basal-like breast cancer, the findings with respect to HGSOC suggest that constitutional BRCA1 methylation could be a risk factor for basal-like breast cancer as well." (PMID 31225507, 2019). "Interestingly, the breast cancer susceptibility gene 1 (BRCA1) and breast cancer susceptibility gene 2 (BRCA2) were found to confer increased susceptibility to colon cancer in a patient with breast cancer under the age of 50 years." (PMID 31183268, 2019).
breast cancer (continued). "We hypothesized that inherited truncating variants in DNA-repair genes, which are partner components of BRCA1 in the maintenance of genome integrity, are likely to interact with BRCA1 by reducing the age at onset of hereditary breast carcinoma." (PMID 31395037, 2019). "Specific inherited mutations in BRCA1 and BRCA2 increase the risk of female breast cancer." (PMID 30956778, 2019). "In Korea, in young breast carcinoma patients under 35 years old with no family histories, the BRCA1/2 mutation prevalence was 10%." (PMID 30713775, 2019). "BRCA1 has also been shown to bind to and regulate miR-155 expression, in breast cancer." (PMID 30323900, 2018). "We therefore investigated their expression patterns in sporadic TCGA breast cancer cases and, consistent with our hypothesis, observed an inverse correlation between BRCA1 and PIN1 expression levels." (PMID 30590041, 2018). "For example, BRCA1 and BRCA2 mutations contribute to only 10% of hereditary breast cancer cases." (PMID 29720094, 2018). "In addition to BRCA1/2, we found pathogenic variants in PTEN are associated with younger age at onset of breast cancer in Japanese women." (PMID 30287823, 2018). "Among the 73 BRCA1/2MUT+ women who underwent BCS, 3 ipsilateral breast cancer cases were found (mean observation period: 3.5 years; incidence rate: 1.2%/year), compared with only 2 cases among the 477 BRCA1/2MUT− women (mean observation period: 2.2 years; incidence rate: 0.2%/year)." (PMID 30203341, 2018). "Use of two short hairpins targeting human LYN demonstrated that LYN knockdown in human breast cancer cells also significantly impaired cell growth in the BRCA1-mutated HCC1937 human breast cancer cell line and in cells from a BRCA1 mutant breast cancer patient-derived xenograft (PDX)." (PMID 30590041, 2018). "We conducted a genome-wide search for BRCAX genes involving 1,469 Korean female breast cancer cases who were eligible for the BRCA1/2 test but negative for causal mutations." (PMID 30323354, 2018). "Breast cancer survivors with BRCA1/2 mutations are three times more likely to develop contralateral breast cancer than non-carriers." (PMID 30227649, 2018). "For this purpose, we utilize HCC1937 BRCA1-deficient breast cancer cells, with or without genetic complementation, and a panel of breast cancer cells in which we knock-down BRCA1 using a shRNA." (PMID 31773035, 2018). "To determine the role of estrogen in Brca1-deficient mammary tumorigenesis, we transplanted Brca1-proficient and Brca1-deficient mammary tumor cells into MFPs of NSG mice with or without estrogen (17β-estradiol, E2) supplement." (PMID 29996906, 2018). "Male breast cancer is rare in the general population with a lifetime risk of 0.1%, although the risk is significantly increased to 7-8% with BRCA2 mutation and 1% with a BRCA1 mutation." (PMID 29433453, 2018). "In this study, we used comprehensive multigene panels that included 35 known or suspected cancer susceptibility genes to examine BRCA1/2 mutation-negative Korean patients who had clinical features indicative of hereditary breast cancer." (PMID 29338689, 2018). "Many of the highly published disease-gene associations may have been studied for reasons that would not be directly reflected in gene expression analysis, including BRCA1 in breast cancer and CD4 in human immunodeficiency virus." (PMID 29358745, 2018).